H3P3 (H3 histone pseudogene 3)
Synonyms: p04
Gene: Processed pseudogene on chromosome 1 (92,749,175 to 92,749,330, reverse strand). Ensembl gene ENSG00000234202.
Diseases named in the same sentence as H3P3 in open-access papers:
H3P3 is named in the same sentence as 7 diseases in open-access papers, as found by Europe PMC text mining. Sharing a sentence is not in itself a finding about the gene and the disease.
H3P3 shares sentences with these, for which no sentence is quoted: tumor (4 papers); cancer (1); glomerulonephritis (1); lung carcinoma (1); lupus (1); pancreatic cancer (1); squamous cell carcinoma (1).